CPEB3 (cytoplasmic polyadenylation element binding protein 3)
Diseases named in the same sentence as CPEB3 in open-access papers (continued):
Sharing a sentence is not in itself a finding about the gene and the disease.
colorectal cancer (continued). "Based on previously published microarray data from the Oncomine database, we first analyzed CPEB3 expression in colorectal cancer tissues and other tumors and identified 10 databases (P < 0.0001; Fold Change >2; Gene Rank <10%) for further analysis." (PMID 33146632, 2020). "Analysis of CPEB3 expression in The Cancer Gene Atlas revealed a similar declining trend in colorectal cancer tissues (P < 0.0001)." (PMID 33146632, 2020). "CPEB3 down-regulation promotes colorectal cancer cell proliferation, migration, and invasion in vitro and in vivo, while up-regulation has an inhibitory effect." (PMID 33146632, 2020). "Here, we showed that CPEB3 anti-tumor effects in colorectal cancer are likely mediated via regulating the JAK/STAT pathway." (PMID 33146632, 2020). "Compared with peri-tumoral tissues, CPEB3 mRNA expression was significantly decreased in colorectal cancer." (PMID 33146632, 2020). "Impairing the JAK/STAT signaling pathway reversed CPEB3-knockdown effects on proliferation, migration, and invasion in colorectal cancer cells." (PMID 33146632, 2020). "For example, given the association of CPEB3 with numerous tumor-progression transcripts, we cannot exclude the possibility that other unidentified molecules or compensatory mechanisms may also contribute to aberrant colorectal cancer proliferation and metastasis." (PMID 33146632, 2020). "Curiously, the CPEB3 gene has been reported to be downregulated in several cancer tissues, including colorectal cancer." (PMID 32962187, 2020). "Some studies have demonstrated that CPEB3 expression was downregulated in colorectal cancer and in human papilloma virus- (HPV-) positive cervical cancers." (PMID 29850575, 2018). "The CPEB3 was reported to support the recruitment of regulatory T cells and lowering the recruitment of immune cells with anti-cancer activity in renal carcinoma, and of anti-inflammatory macrophages in colorectal carcinoma." (PMID 41349485, 2025). "In addition, CPEB3 over-expressing colorectal cancer cells exhibited reduced activity in cancer-related signal pathways, including cell adhesion, apoptosis, JAK/STAT, and Toll-Like-receptor." (PMID 33146632, 2020). "In addition, CPEB3 is a tumor suppressor, inhibiting cell proliferation and migration in colorectal cancer cells through regulating the JAK/STAT pathway." (PMID 33146632, 2020). "Moreover, CPEB3 down-regulation in colorectal cancer cells increased migration and invasion, while up-regulation showed the opposite effect." (PMID 33146632, 2020). "In addition, CPEB3 attenuates colorectal cancer cell proliferation, while silencing the protein enhances proliferation rate in vitro and in athymic nude mice." (PMID 33146632, 2020). "CPEB3 is downregulated in colorectal cancer, human HCC, and cervical cancer." (PMID 29850575, 2018). "Moreover, a microarray-based, high throughput screening study for unknown tumor-suppressor genes in colorectal cancer identified CPEB3 as one of four significantly down-regulated genes." (PMID 33146632, 2020). "In colorectal cancer (CRC), CPEB3 is involved in the crosstalk between cancer cells and TAMs by targeting IL-6R/STAT3 signalling." (PMID 38987822, 2024). "Knockdown of CPEB3 induced active JAK-STAT signaling, thereby triggering the proliferation and metastasis capacity of colorectal cancer cells." (PMID 33146632, 2020). "Altogether, these results revealed that there is a mechanistic connection between CPEB3 and the JAK/STAT signal pathway, potentially via direct binding to JAK1 3’UTR in colorectal cancer cells." (PMID 33146632, 2020). "Therefore, CPEB3 appears to exert primarily a negative effect on gene expression and tumor-related pathways in colorectal cancer cells." (PMID 33146632, 2020). "Thus, the anti-tumorous effects of CPEB3 may not be restricted to colorectal cancer and requires further exploration in other digestive tract cancers." (PMID 33146632, 2020).
cervical cancer (6 papers, 2018 to 2025). A primary or metastatic malignant neoplasm involving the cervix. "•MiR-21-5p inhibitor enhances the radio-sensitivity of cervical cancer cells via blocking CPEB3/CDK1/Cyclin B pathway." (PMID 40746848, 2025). "In conclusion, LINC00641 can competitively bind miR-378a-3p through the ceRNA mechanism, so as to increase the expression of CPEB3 mRNA and inhibit the proliferation, migration and invasion of cervical cancer cells." (PMID 35155216, 2021). "Moreover, the role of CPEB3 in the progression of cervical cancer as well as in tumorigenesis and metastasis of lung adenocarcinoma was shown." (PMID 34944712, 2021). "The experiment proved that LINC00641 competed with CPEB3 and bound to miR-378a-3p, confirming that LINC00641 regulated the progression of cervical cancer by up regulating CPEB3." (PMID 35155216, 2021). "CPEB3 has low expression in colon cancer and HPV-positive cervical cancer, which indicates it may be involved in tumorigenesis as a tumor suppressor, but the specific mechanism still needs further study." (PMID 34879089, 2021).
gastric cancer (4 papers, 2020 to 2024). A primary or metastatic malignant neoplasm involving the stomach. "Remarkably, CPEB3 re-expression inhibited gastric cancer growth and metastasis by decreasing ADAR1 expression, opening a therapeutic opportunity." (PMID 37369946, 2023). "In addition, cytoplasmic polyadenylation element-binding protein 3 (CPEB3) inhibits ADAR1-mediated RNA editing by localizing ADAR1 mRNA to the processing body (P-body), inhibiting the translation of ADAR1, thereby suppressing gastric cancer progression." (PMID 38233935, 2024).
lung carcinoma (4 papers, 2017 to 2024). "Another peak of homozygous deletions targets CPEB3, mostly in lung cancer." (PMID 29089486, 2017).
glioblastoma (3 papers, 2016 to 2022). The most malignant astrocytic tumor (WHO grade IV). "Additionally, CPEB4 mRNA is upregulated in pancreatic carcinomas and glioblastomas, while CPEB3 mRNA is consistently downregulated in digestive tract tumors." (PMID 33146632, 2020).
melanoma (3 papers, 2016 to 2021). A malignant, usually aggressive tumor composed of atypical, neoplastic melanocytes. "Here, our current study was aimed at focusing on the association of CPEB3 and prognosis of melanoma." (PMID 33506034, 2021). "Melanoma with low CPEB3 expression was associated with worse OS (overall survival), progression-free survival (PFS), and disease-specific survival (DSS) than in that with high expression." (PMID 33506034, 2021). "GSEA results showed that CPEB3-related melanoma consisted of many key pathways and was associated with tumorigenesis." (PMID 33506034, 2021). "Indeed, higher CPEB3 expression was associated with improved patient survival of melanoma." (PMID 33506034, 2021). "In the univariate analysis, expression of CPEB3, melanoma ulceration, Clark level of melanoma, age, clinical stage, T stage, and N stage were correlated with OS (p < 0.05)." (PMID 33506034, 2021). "Although our analysis in the current study improved our understanding of the relationship between CPEB3 and melanoma, there were still some limitations." (PMID 33506034, 2021). "In the univariate analysis, the melanoma Clark level, melanoma ulceration, clinical stage, T stage, N stage, age, and expression of CPEB3 affected the prognosis of melanoma patients (all p < 0.05)." (PMID 33506034, 2021). "CPEB3 is correlated with several critical pathways in melanoma, including PD1 signaling, CTLA4 pathway, CTCF pathway, CHEMOKIN signaling, VEGF signaling, and JAK-STAT pathway." (PMID 33506034, 2021). "Further analysis by multivariate Cox regression showed that N stage (p = 0.029), melanoma ulceration (p = 0.004), and CPEB3 expression (p < 0.001) were independent prognostic factors of OS in melanoma." (PMID 33506034, 2021). "Results from our study showed that CPEB3 expression was downregulated in melanoma compared to normal tissues, indicating a potential function for CPEB3 in tumorigenesis." (PMID 33506034, 2021). "The aim of this study was to investigate the role of CPEB3 in predicting the prognosis of melanoma patients." (PMID 33506034, 2021). "We also found that CPEB3 was downregulated in melanoma with a higher clinicopathological grade, such as T staging, clinical staging, melanoma Clark level, and melanoma ulceration." (PMID 33506034, 2021). "Levels of CPEB3 were rather similar in all cell lines studied (see legends for P values of pairwise comparisons to melanoma)." (PMID 27857118, 2016). "Together, these findings indicated that CPEB3 may play a crucial role in immune infiltration and serve as a potential biomarker in the diagnosis and prognosis of melanoma." (PMID 33506034, 2021). "In addition, the tissue microenvironment of tumor cells is an important factor of tumors; thus, we also explored the relevance between immune cells and CPEB3 in the immune microenvironment of melanoma." (PMID 33506034, 2021). "We evaluated the correlation between CPEB3 and 24 immune cell subsets in melanoma and found that CPEB3 has a close positive correlation with cytotoxic cells, Th1 cells, and CD8 T cells; CPEB3 has a close negative correlation with mast cells, NK cells, and Th17 cells." (PMID 33506034, 2021). "The decrease in CPEB3 expression in melanoma was significantly correlated with T staging (p < 0.001), clinical staging (p = 0.029), melanoma Clark level (p = 0.014), and melanoma ulceration (p = 0.003), while it was marginally significant in N staging (p = 0.089)." (PMID 33506034, 2021). "CPEB3 is an excellent candidate as a potential prognostic marker in melanoma." (PMID 33506034, 2021). "In summary, low expression of CPEB3 is related to a higher grade and poor prognosis of melanoma." (PMID 33506034, 2021). "Moreover, the expression of CPEB3 in melanoma is related to the level of immune infiltration." (PMID 33506034, 2021). "Therefore, we investigated whether the expression of CPEB3 is related to the level of immune infiltration in melanoma." (PMID 33506034, 2021).
melanoma (continued). "CPEB3 may be a potential prognostic marker in melanoma with poor survival." (PMID 33506034, 2021). "As the case of melanomas, melanocytes also expressed CPEB1, CPEB2 and CPEB3, but these proteins appear to be unable to compensate for CPEB4 depletion." (PMID 27857118, 2016). "Cytoplasmic polyadenylation element-binding protein 3 (CPEB3) has been acknowledged as a tumor-suppressive gene in several cancers; however, there are few reports on the clinical significance of CPEB3 in melanoma." (PMID 33506034, 2021). "As far as we know, the function of CPEB3 in melanoma has not been reported." (PMID 33506034, 2021). "Similarly, there are no reports of the CPEB family members CPEB2, CPEB3 and CPEB4 in melanoma." (PMID 27857118, 2016).
liver cancer (2 papers, 2020 to 2021). An epithelial or non-epithelial malignant neoplasm that arises from the liver. "While our research group firstly reported that CPEB3 involved in the regulation of liver cancer progression." (PMID 32968053, 2020).
osteosarcoma (2 papers, 2021). A usually aggressive malignant bone-forming mesenchymal neoplasm, predominantly affecting adolescents and young adults. "Our results showed that compared with osteoblasts, CPEB3, EIF4E3, RBM34, RPS27L, RPS29 and TDRD6 were down-regulated in U2OS and 143B, while NXT2, TERT, TLR8 and ZC3HAV1 were up-regulated in osteosarcoma cells." (PMID 34926575, 2021).
status epilepticus (2 papers, 2016 to 2025). Status epilepticus is defined as a continuous seizure lasting more than 30 min, or two or more seizures without full recovery of consciousness between any of them. "Interestingly, status epilepticus induced by systemic kainate injection in mice led to specific upregulation of the CPEB3 isoforms containing exon seven." (PMID 26915047, 2016).
Anxiety (1 paper, 2016). Intense feelings of nervousness, tension, or panic often arise in response to interpersonal stresses. "Interestingly, CPEB3-KO mice exhibited anxiety-like responses with reduced exploratory behaviors in the open field assay, which suggests that CPEB3-suppressed TRPV1 expression may also occur in the brain." (PMID 26915043, 2016).
astrocytomas (1 paper, 2016). "PKA and CaMKII kinases showed predominant activity in human astrocytomas, which were also positive for phospho-CPEB3." (PMID 27256982, 2016).
behavioral disorders (1 paper, 2025). "Notably, genes associated with immune modulation and inflammation (e.g., Dusp1, Lrrc39, E2f2), neuroplasticity and memory (e.g., Cpeb3, Efnb3), and behavioral disorders (e.g., Pla2g4c) exhibited substantial changes." (PMID 40285614, 2025).
cognitive disorder (1 paper, 2021). A disease affects cognitive processes. "All these results might suggest a hypothesis that IE2 causes cognitive disorder in UL122 mice by upregulating CPEB3 and therefore downregulating PRPs, that results in the impairment of synaptic plasticity and development of dendritic cells." (PMID 34790111, 2021).
Cognitive impairment (1 paper, 2021). Abnormal cognition is characterized by deficits in thinking, reasoning, or remembering. "As PRPs reduced CPEB3 elevated simultaneously in UL122 mice, and in our previous publications, the expression of NR1 was abnormal in UL122 mouse, it could be proposed that IE2-CPEB3-mediated PRPs might represent a novel mechanism underlying the cognitive impairment in the UL122 mice." (PMID 34790111, 2021). "In the UL122 mice, the increased expression of CPEB3 induced by long-term stably expressed IE2 impaired synaptic plasticity through downregulating the expression of PRPs (PSD95 and MAP2), finally resulting in cognitive impairment." (PMID 34790111, 2021).
depression (1 paper, 2014). "Although several forms of LTP and LTD in the adult SC-CA1 KO synapses appear normal, we identified a specific type of synaptic depression, 3 min of 5-Hz stimulus-evoked DPT, that is impaired without CPEB3." (PMID 25404896, 2014).
epilepsy (1 paper, 2025). A brain disorder characterized by episodes of abnormally increased neuronal discharge resulting in transient episodes of sensory or motor neurological dysfunction, or psychic dysfunction. "Bioinformatics analyses initially suggested that CPEB3 could be associated with epilepsy, and further experiments confirmed that CPEB3 expression was reduced in both epilepsy mouse models and patients with TLE." (PMID 39994587, 2025). "We found that CPEB3 was closely linked to epilepsy using bioinformatics analysis." (PMID 39994587, 2025). "In summary, we speculate that downregulation of CPEB3 gene may be associated with epilepsy." (PMID 39994587, 2025). "CPEB3 was expressed at low levels in the brain tissues of patients with epilepsy and epileptic mouse models, and CPEB3 co-localized with neurons." (PMID 39994587, 2025). "This study provides new evidence for the role of CPEB3 in epilepsy, but further studies are needed in the future to overcome these limitations to gain a more comprehensive understanding of the mechanism of action of CPEB3." (PMID 39994587, 2025). "RT-qPCR results showed that only CPEB3 mRNA was reduced in both hippocampus and cortex of epilepsy mice compared with control group." (PMID 39994587, 2025). "Changes in expression and cellular localization of CPEB3 in epilepsy were verified by western blotting (WB) and Immunofluorescence staining." (PMID 39994587, 2025). "The results were that CPEB3 was downregulated epilepsy in model mice and patients with temporal lobe epilepsy and co-expressed with neurons." (PMID 39994587, 2025). "Our findings provide new insights into the potential mechanisms of CPEB3 in epilepsy." (PMID 39994587, 2025). "In conclusion, CPEB3 may play a role in the pathogenesis of epilepsy, but its molecular mechanism needs to be further explored." (PMID 39994587, 2025). "Behavioral experiments have shown that CPEB3 negatively regulates epilepsy phenotype in mice." (PMID 39994587, 2025). "This suggests that CPEB3 may play a role in the pathology of epilepsy by regulating the expression of the NMDAR subunit." (PMID 39994587, 2025). "In this study, we investigated the mechanism of action of CPEB3 using a mice model of epilepsy." (PMID 39994587, 2025). "This suggests that CPEB3 may alters the epilepsy phenotype by inhibiting the transcriptional activity of STAT3." (PMID 39994587, 2025). "Notably, the gene of CPEB3 was downregulated in epilepsy patients." (PMID 39994587, 2025). "This suggests that CPEB3 may be closely related to epilepsy." (PMID 39994587, 2025). "These experimental results suggest that CPEB3 may be closely related to epilepsy." (PMID 39994587, 2025). "Consequently, we speculated that CPEB3 can reduce STAT3-mediated transcription of NMDARs by inhibiting STAT3 translation in epilepsy." (PMID 39994587, 2025). "Therefore, we investigated whether CPEB3 regulates NMDARs expression in epilepsy." (PMID 39994587, 2025). "Further mechanistic studies revealed that exogenous overexpression of CPEB3 inhibited STAT3 translation and STAT3-mediated transcriptional activity of NMDARs, thereby suppressing NMDAR subunit expression and attenuating epilepsy phenotype in mice." (PMID 39994587, 2025). "Cytoplasmic polyadenylation element-binding protein 3 (CPEB3) regulates neuronal excitability, but its mechanism of action in epilepsy is not clear." (PMID 39994587, 2025). "We injected WP1066 (a STAT3 inhibitor) intraperitoneally into knockdown CPEB3 mice and examined the protein and mRNA expression of GluN1, GluN2A, and GluN2B to verify whether CPEB3 inhibits the transcriptional activity of NMDARs via STAT3 in epilepsy." (PMID 39994587, 2025). "However, whether CPEB3 plays a role in epilepsy has not yet been investigated." (PMID 39994587, 2025).
female subfertility (1 paper, 2024). "Here, we generated an experimental model for the CPEB3 deficiency that leads to female subfertility." (PMID 38786074, 2024). "We hypothesize that the complete absence of CPEB3 in the oocyte would lead to female sterility due to impaired developmental competence of the oocyte." (PMID 38786074, 2024).
fragile X syndrome (1 paper, 2025). A genetic syndrome caused by mutations in the FMR1 gene which is responsible for the expression of the fragile X mental retardation 1 protein. "CPEB3 has been implicated in the neurodevelopmental disorder Fragile X Syndrome (FXS)." (PMID 40916649, 2025).
intrahepatic cholangiocarcinoma (1 paper, 2023). A carcinoma that arises from the intrahepatic bile duct epithelium in any site of the intrahepatic biliary tree. "So, due to its regulation of Gdf9 expression in oocytes, CPEB3 is crucial for the growth of ovarian follicles and female fertility. hsa_circ_0050898, which was derived from the ACTN4 gene’s exons 1 to exons 20, was overexpressed in intrahepatic cholangiocarcinoma." (PMID 36827016, 2023).
neuroblastoma (1 paper, 2023). Neuroblastoma (NB) is the most common solid, extracranial childhood tumor. "To verify that the S240-242A mutant is excluded from P bodies and neuronal RNP granules, we compared the interactome of mouse neuroblastoma N2A-expressed CPEB3 and S240-242A." (PMID 36716374, 2023).